MTAP (methylthioadenosine phosphorylase)
Diseases named in the same sentence as MTAP in open-access papers (continued):
Sharing a sentence is not in itself a finding about the gene and the disease.
lymphoma (17 papers, 2013 to 2025). A malignant (clonal) proliferation of B- lymphocytes or T- lymphocytes which involves the lymph nodes, bone marrow and/or extranodal sites. "In a study on 13,067 cancers from 149 different tumor types we had earlier found that MTAP deficiency is unrelated to 9p21 deletions in several tumor types including malignant lymphoma and neuroendocrine neoplasms of various organs." (PMID 40554389, 2025). "Clinical trials of AG-270 (NCT03435250) on patients with advanced solid tumors or lymphoma with MTAP loss have been terminated due to liver toxicity and disease progression." (PMID 41439984, 2025). "Among these, AG-270, IDE397, S-095035, and ISM3412 are currently undergoing clinical trials to treat MTAP-deficient solid tumors and lymphomas." (PMID 40430461, 2025). "Participants with advanced solid tumors or lymphoma With MTAP loss." (PMID 36358940, 2022). "Loss of MTAP expression is frequent in a large number of different human tumors including leukemias, lymphomas, mesothelioma, lung carcinoma, pancreatic carcinoma, squamous cell carcinoma, biliary tract cancer, glioblastoma, osteosarcoma, and neuroendocrine tumors." (PMID 23840755, 2013). "Currently, clinical trials of therapies targeted at tumors with MTAP loss are centered on solid tumors including sarcomas, carcinomas, and lymphomas with homozygous MTAP deletion." (PMID 41439984, 2025). "Currently there is a phase I clinical trial investigating the MAT2A inhibitor AG-270 in advanced solid tumors or lymphomas with homozygous deletions of CDKN2A/B or MTAP (NCT03435250)." (PMID 38017560, 2023). "In comparison with normal controls, levels of MTAP, RNA, and MTAP expression by IHC were significantly reduced in the tissues in these mice infiltrated with lymphoma." (PMID 37894345, 2023). "CDKN2A and MTAP genes, which have also been described in lymphomas, specifically in the chemoresistant and ABC type DLBCLs }, were in turn located in the regions of copy number losses at 9p21.3." (PMID 24625556, 2014). "Dose-escalation, phase I study in advanced solid tumors or lymphoma with homozygous MTAP deletion was realized and is now terminated due to changes in the study strategy (introduction of combination therapies instead of AG 270 monotherapy in subsequent studies)." (PMID 41465382, 2025). "In contrast to pancreatic adenocarcinomas, MTAP deficiency usually occurs in the absence of 9p21 deletions in malignant lymphomas and neuroendocrine neoplasms." (PMID 40227771, 2025). "In a number of other cancers, such as lymphomas, gastric cancers, hepatocellular carcinoma (HCC), and nasopharyngeal carcinomas, reduced MTAP expression is associated with promoter hypermethylation, which produces similar functional loss as tumors with homozygous deletion of the MTAP gene." (PMID 41439984, 2025).
osteosarcoma (15 papers, 2004 to 2025). A usually aggressive malignant bone-forming mesenchymal neoplasm, predominantly affecting adolescents and young adults. "The phase I/II trial of the MAT2A inhibitor SCR6639 (NCT04930081) included 43 patients with MTAP-deficient advanced osteosarcoma." (PMID 41142821, 2025). "As for low mRNA expression, soft tissue sarcoma (20%), osteosarcoma (16%), and fallopian tube cancer (14%) showed the highest percentage of MTAP loss." (PMID 41439984, 2025). "present a high-resolution single-cell atlas of MTAP-deleted osteosarcoma, revealing deficiency in CD8A+ T cells." (PMID 39983717, 2025). "In response to the unique metabolic dependence of MTAP-deficient osteosarcoma, researchers proposed an innovative strategy of methionine intervention combined with ICIs." (PMID 41142821, 2025). "The authors suggested that the MTAP deficiency frequently observed in osteosarcoma can be targeted with inhibitors of de novo purine synthesis, as a potential chemotherapy strategy for MTAP-negative osteosarcoma patients." (PMID 36913304, 2023). "MTAP encodes methylthioadenosine phosphorylase, essential for adenine and methionine synthesis, and was deleted in 38 % of osteosarcoma tumors." (PMID 26672768, 2016). "In their study, MTAP-null and MTAP-knockout (MTAP-KO) osteosarcoma cell lines were found to be more sensitive to rMETase than MTAP-wild type (MTAP-WT) cell lines, suggesting increased methionine dependency in cells without MTAP." (PMID 41439984, 2025). "Methionine restriction or MAT2A inhibitor SCR6639 increases CD8A+ T cell infiltration in the tumor microenvironment, enhancing the efficacy of immune checkpoint therapy in MTAP-deleted osteosarcoma." (PMID 39983717, 2025). "These microrobots could selectively inhibit the tumor growth of the MTAP-deleted osteosarcoma in a simulation in vitro." (PMID 35875497, 2022). "Previously, one of these nearby protein-coding genes (MTAP) was identified in osteosarcoma." (PMID 34681828, 2021). "In our previous study, we established a clinical cohort Shanghai General Hospital—Osteosarcoma (SGH-OS) through multi-omics analysis and we identified a frequent genomic Chr9p21.3 deletion in OS16 leading to MTAP deletion in OS, consistent with previous study." (PMID 39983717, 2025). "We further demonstrated that exosomal RNAs including Annexin2, Smad2, MTAP, CIP4, PEDF, WWOX, Cdc5L, P27, could also discriminate good and poor chemotherapeutic response for osteosarcoma treatment." (PMID 29100284, 2017).
colorectal cancer (13 papers, 2016 to 2025). A primary or metastatic malignant neoplasm that affects the colon or rectum. "For example, loss of MTAP is associated with lower microsatellite instability and tumor mutation burden in colorectal cancer." (PMID 41439984, 2025). "In colorectal cancer, MTAP loss was rare (1.1%), while most MTAP alterations were mutations (5/7, 71.4%); among the latter, only MTAP-CDKN2B truncation led to protein loss, thus potentially actionable." (PMID 38350716, 2025). "HCT116 MTAP WT and MTAP-/- colorectal cancer cells constitute an isogenic pair which has served as the model system to benchmark synthetic lethal PRMT5 inhibitors." (PMID 41339334, 2025). "This quantitative capability can be leveraged to stratify cofactor-sensitivity and intracellular ternary complex formation in MTAP-deleted colorectal cancer cells." (PMID 41339334, 2025). "This is supported by prior studies in colorectal cancer that found a positive correlation between MTAP expression and tumor proliferation, migration, and invasion through epithelial–mesenchymal transition (EMT)." (PMID 41439984, 2025). "We used an isogenic pair of HCT116 colorectal cancer cell lines that are MTAP WT (Parental HCT116 cells) or have been rendered MTAP-deleted using CRISPR technology, respectively." (PMID 40377999, 2025). "MAT2a inhibitors are now in clinical trials for genotypic MTAP−/− cancers, however the MTAP−/− genotype represents fewer than 2% of human colorectal cancers (CRCs), limiting the utility of MAT2a inhibitors in these and other MTAP+/+ cancers." (PMID 38000655, 2024). "MTAP-loss was most prevalent in pancreatic ductal adenocarcinoma (PDAC) at 21.7% and least in colorectal carcinoma (CRC) at 1.1%." (PMID 38330461, 2024). "Challenges for the use of MAT2a inhibitors include the variable frequency of the MTAP−/− genotype, which ranges from 55% prevalence in glioblastoma to 2% in colorectal carcinoma, limiting the broader application of these therapeutics." (PMID 38000655, 2024). "In colorectal cancer, downregulation of MTAP can also influence the epithelial-to-mesenchymal shift and stimulate tumor growth and metastasis." (PMID 36913304, 2023). "Other MTAP alterations were found in colorectal cancer, but unlikely to cause protein loss and drug susceptibility." (PMID 38350716, 2025). "Downregulation of MTAP can also modulate EMT and promote growth and metastasis in colorectal cancer." (PMID 35541910, 2022). "The results of coexpression analysis coupled to ENCODE ChIP-Seq data strongly suggest c-Myc and C/EBPβ as regulators of the expression of key enzymes of polyamine metabolism that are upregulated in colorectal cancer: SMOX, AZIN1, MTAP, SRM, AMD1, ODC1, and AGMAT." (PMID 27433286, 2016). "Moreover, even in tumor models without MTAP deletion, pharmacological inhibition of MTAP using methylthio‐DADMe‐immucillin‐A (MTDIA) successfully induced an MTAP‐depleted state in colorectal cancer cells, and the combination of MTDIA and the MAT2A inhibitor AG‐270 exhibited synthetic lethality." (PMID 40552664, 2025).
sarcoma (13 papers, 2014 to 2026). A usually aggressive malignant neoplasm of the soft tissue or bone. "Loss of MTAP, which functions as a tumor suppressor and is vital for methionine salvage, has been observed in a spectrum of cancers including melanoma and sarcoma." (PMID 30314519, 2018). "We also corroborated the suppressive role of MTAP in metastasis, which is the leading cause of sarcoma-associated mortality and critically involves the regulation of cell motility and transgression through an extracellular matrix." (PMID 25426549, 2014). "The fourth gene deregulated in TFCP2-rearranged sarcoma, besides ALK, CDKN2A, and MTAP, is TERT, encoding the catalytic component of the telomerase complex that protects dividing cells from progressive telomere shortening, subsequent senescence, and malignant transformation." (PMID 38168093, 2024). "Therefore, PRMT5 inhibitors and antifolate drugs may be potential therapeutic options to pursue in TFCP2 fusion sarcomas with MTAP deletion." (PMID 40361368, 2025). "Taken together, TFCP2-rearranged sarcoma likely represents a separate entity characterized by distinct transcriptional and DNA methylation profiles, an unusual degree of genomic instability, truncated ALK variants, ALK and TERT overexpression, and recurrent CDKN2A/MTAP co-deletions." (PMID 38168093, 2024). "The efficacy of PRMT5 inhibitors in the context of MTAP passenger deletions has been demonstrated in several cancers, suggesting that patients with FUS/EWSR1-TFCP2 sarcoma and CDKN2A/MTAP loss may also benefit from PRMT5 inhibitors, which are currently being tested in clinical trials." (PMID 38168093, 2024). "Variants in COL7A1 and MTAP were not reported in ClinVar; however, variants in these genes are related to squamous cell carcinoma (as part of epidermolysis bullosa spectrum) and sarcoma." (PMID 32443704, 2020). "Because MTAP is linked to polyamine metabolism and adenine and methionine salvage, examining whether MTAP inactivation promotes angiogenesis by perturbing the metabolic balance of sarcoma cells is conceivable, similar to the scenario involved in deregulated ASS1." (PMID 25426549, 2014). "Interestingly, this research has pointed to the role of the gene coding for methylthioadenosine phosphorylase, often codeleted with p16 (CDKN2A), particularly in MM and several types of sarcomas." (PMID 33207594, 2020). "Finally, our findings suggest that patients with TFCP2-rearranged sarcomas, which are refractory to conventional chemotherapy, may benefit from combination treatments that include platinum derivatives, ALK inhibitors, and, in the case of CDKN2A/MTAP co-deletions, drugs targeting PRMT5." (PMID 38168093, 2024).
bladder cancer (12 papers, 2010 to 2026). "Many cancers, including bladder cancer, are deficient of the MTAP enzyme because the gene is co-deleted along with the tumor suppressor p16." (PMID 20059769, 2010). "Methylthioadenosine phosphorylase (MTAP)-deficient tumors account for ~15% of solid tumors, including ~15% of NSCLC, 28% of esophageal cancer, 26% of bladder cancer, and 10% of esophagogastric cancer." (PMID 37699892, 2023). "The staining conditions had been titrated by using a TMA composed of 20 wild-type cells and 20 heterozygously and 20 homozygously MTAP-deleted bladder cancers to obtain maximal staining intensity in wild-type cells while retaining a complete absence of background staining in MTAP-deficient cancers." (PMID 40227771, 2025). "This study provides initial evidence of intratumoral PON1 expression in bladder cancer and suggests that combined PON1/MTAP immunohistochemical assessment may reflect tumor grade and biological behavior." (PMID 41750579, 2026).
hepatocellular carcinoma (12 papers, 2013 to 2025). A malignant tumor that arises from hepatocytes. "Instead of genomic losses, promoter hypermethylation represents the preponderant inactivating mechanism in MTAP-deficient hepatocellular carcinomas." (PMID 25426549, 2014). "Kiroviski reported that MTAP knockdown upregulated MMP-9 expression through the accumulation of 5′-deoxy-5′-methylthioadenosine in hepatocellular carcinomas." (PMID 25426549, 2014). "Recently, we have shown downregulation and tumor suppressor activity of MTAP in hepatocellular carcinoma (HCC)." (PMID 24324622, 2013). "Our findings are consistent with reports that MTAP expression in gastric carcinoma cells inhibits migration in a wound-healing assay, and that inhibition of MTAP causes increased expression of MMP-1 and MMP-9 in a human hepatocellular carcinoma cell line." (PMID 25387827, 2014). "MTAP-loss occurs in 22% of PDAC, 15% of IHCC, 8.7% of gastroesophageal adenocarcinoma, 2.4% of hepatocellular carcinoma, and 1.1% of CRC and is not mutually exclusive with other targetable mutations." (PMID 38330461, 2024). "Furthermore, it was observed in hepatocellular carcinoma that the re-expression of MTAP did not change the proliferation rates when compared to mock controls." (PMID 32093414, 2020).
astrocytoma (10 papers, 2016 to 2025). "In this study, the T2-FLAIR mismatch sign was associated with the expression of MTAP in IDH-mutant astrocytoma." (PMID 39117984, 2024). "In the astrocytoma group, the first observer detected MTAP loss in 23 (23.9%) of the tumors, and the second observer detected MTAP loss in 22 (23.9%) of them." (PMID 38109891, 2024). "Among the astrocytomas, the sensitivity of MTAP for the first observer was 90%, and the specificity was 95.59%, while the sensitivity for the second observer was 85%, and the specificity was 95.59%." (PMID 38109891, 2024). "Eighty-eight astrocytomas and 71 oligodendrogliomas cases that were diagnosed between 2014 and 2021 at Hacettepe University were selected and tissue microarrays were conducted to perform CDKN2A fluorescence in situ hybridization and MTAP IHC." (PMID 38109891, 2024). "Thirty-one cases of astrocytoma, IDH-mutant with MTAP results by IHC were included in this study." (PMID 39117984, 2024). "None of the astrocytoma, IDH-mutant showed loss of MTAP immunohistochemical staining." (PMID 39133381, 2024).
pleural mesothelioma (10 papers, 2022 to 2026). A neoplasm that arises from the mesothelial cells of the pleura. "in pleural mesothelioma, raising concerns about the diagnostic utility of MTAP IHC in peritoneal mesothelioma." (PMID 40566743, 2025). "CDKN2A deletion is a common alteration in pleural mesothelioma (PM) and frequently associated with co-deletion of MTAP." (PMID 37894345, 2023). "Early clinical data regarding MRTX1719 show activity across different tumor types, with responses seen in patients with MTAP-deleted pleural mesothelioma, melanoma, gallbladder adenocarcinoma, NSCLC, and malignant peripheral nerve sheath tumors." (PMID 38610930, 2024). "Loss of MTAP expression and CDKN2A homozygous deletion (detected by FISH) could be helpful in pleural mesothelioma diagnosis." (PMID 39409918, 2024). "MTAP immunohistochemistry (IHC) has been proposed as a cheaper and more reproducible surrogate for CDKN2A homozygous deletion (HD) detected by FISH in pleural mesothelioma." (PMID 40566743, 2025). "Specifically, we confirmed that the profiles corresponded to expected pleural mesothelioma-specific alterations, including changes in the BAP1 and MTAP/CDKN2A gene regions." (PMID 39920655, 2025). "Along with the 2021 WHO Classification of Thoracic Tumours, recent literature on the topic states that MTAP immunohistochemistry is a highly specific and sensitive surrogate of FISH to detect CDKN2A HD in pleural mesothelioma." (PMID 40566743, 2025). "MTAP deletions are detected in two thirds of MPMs and occur as codeletions with CDKN2A in the majority of pleural mesotheliomas." (PMID 38610930, 2024). "Cytological diagnosis of pleural mesothelioma (PM) is controversial, even using ancillary markers (BAP1, MTAP and CDKN2A)." (PMID 38067238, 2023). "The five most frequently altered genes in pleural mesothelioma were CDKN2A (48.2%), BAP1 (45.0%), CDKN2B (42.2%), NF2 (32.8%) and MTAP (32.3%), in peritoneal mesothelioma BAP1 (47.9%), NF2 (26.5%), CDKN2A (25.9%), CDKN2B (19.5%), PBRM1 (15.8%)." (PMID 36138075, 2022). "The immunohistochemical MTVT profile is similar to that of pleural mesothelioma, including the expression of calretinin, WT1, and D2-40; MTAP and BAP-1 expression may be lost." (PMID 39682143, 2024).
lung adenocarcinoma (9 papers, 2016 to 2025). A carcinoma that arises from the lung and is characterized by the presence of malignant glandular epithelial cells. "An analysis of a lung adenocarcinoma retrospective cohort (n = 72) from the BATTLE2 clinical trial (ClinicalTrials.gov ID: NCT01248247) revealed that MTAP deficiency correlates with a heightened response rate to pemetrexed." (PMID 38001653, 2023). "EMT is also promoted by the purine metabolic enzyme MTAP (methylthioadenosine phosphorylase), which is downregulated in lung adenocarcinoma and predicts prognosis." (PMID 36980828, 2023). "MTAP expression in tumor specimens from 101 Taiwanese diagnosed with lung adenocarcinoma was detected by using RT‐qPCR assays." (PMID 35766227, 2022). "However, regardless of the excellent blockades of purine synthesis on pemetrexed to MTAP-deficient lung adenocarcinoma cell lines in basic research, it is still unclear whether MTAP deficiency could predict the sensitivity of pemetrexed-based treatments in lung adenocarcinoma clinically." (PMID 31965001, 2020). "Therefore, we conducted this retrospective study to explore the correlation between MTAP expression and clinical outcomes in patients with advanced lung adenocarcinoma who received pemetrexed-based first-line chemotherapy." (PMID 31965001, 2020). "It is concluded that MTAP-low expression could predict improved treatment response but worsened survival in advanced lung adenocarcinoma." (PMID 31965001, 2020). "To further address the clinical relevance of this hypothesis, we first utilized our proteomic and transcriptomic data from a prospectively collected lung adenocarcinoma cohort of Taiwan Cancer Moonshot to examine the correlation between MTAP/vimentin and PRMT5/vimentin." (PMID 35766227, 2022). "Among a total of 200 patients, we identified a cohort of 72 patients with lung adenocarcinoma (LUAD) who were treated with pemetrexed plus carboplatin and had tumor RNA expression data on both the MTAP and CDKN2A genes." (PMID 35379845, 2022). "Now, we are screening some lung adenocarcinoma cell lines harboring gene mutations, such as EGFR mutations, ALK rearrangement, KRAS mutations, and BRAF mutation, and other cell lines without gene mutations to detect MTAP gene and protein expression." (PMID 31965001, 2020).